NCF4 (neutrophil cytosolic factor 4)
Description:
Subunit of the phagocyte NADPH oxidase complex that mediates the transfer of electrons from cytosolic NADPH to O2 to produce the superoxide anion (O2(-)) (Probable). In the activated complex, electrons are first transferred from NADPH to flavin adenine dinucleotide (FAD) and subsequently transferred via two heme molecules to molecular oxygen, producing superoxide through an outer-sphere reaction (By similarity). Activation of the NADPH oxidase complex is initiated by the assembly of cytosolic subunits of the NADPH oxidase complex with the core NADPH oxidase complex to form a complex at the plasma membrane or phagosomal membrane (By similarity). This activation process is initiated by phosphorylation dependent binding of the cytosolic NCF1/p47-phox subunit to the C-terminus of CYBA/p22-phox (By similarity).
Synonyms: p40phox; SH3PXD4; CGD3; NCF
Tractability: Small molecule: a structure with a bound ligand is known. Antibody: UniProt places it where antibodies can reach, with high confidence. PROTAC: ubiquitination databases record sites on it; its protein half-life has been measured.
Safety:
Unwanted effects reported when the protein is acted on. In parentheses: how it was acted on, where the effect was seen, and who reports it.
cardiotoxicity (source: ClinPGx)
Gene: Protein-coding gene on chromosome 22 (36,860,988 to 36,878,017, forward strand). Ensembl gene ENSG00000100365.
Subcellular location: Cytoplasm, cytosol; Endosome membrane; Membrane
Subcellular location (Human Protein Atlas): Cytosol
Pathways (Reactome):
Signal Transduction: RAC1 GTPase cycle; RAC2 GTPase cycle; RAC3 GTPase cycle; RHO GTPases Activate NADPH Oxidases; VEGFA-VEGFR2 Pathway
Immune System: Cross-presentation of particulate exogenous antigens (phagosomes); ROS and RNS production in phagocytes
Cellular responses to stimuli: Detoxification of Reactive Oxygen Species
Gene Ontology:
Molecular function: phosphatidylinositol-3-phosphate binding; protein binding; superoxide-generating NADPH oxidase activator activity; phosphatidylinositol binding
Biological process: superoxide anion generation; respiratory burst; phagocytosis
Cellular component: cytosol; endosome membrane; membrane; NADPH oxidase complex; cytoplasm; phagolysosome; plasma membrane
Genetic constraint (gnomAD): Loss-of-function variants: 30 observed, 40.47 expected, observed/expected ratio (o/e) 0.74, 90% interval 0.55 to 1. The upper end of that interval is the gene's LOEUF score, 1, which puts it in group 4 of 6, group 1 being the genes least tolerant of losing a copy. Missense variants: 432 observed, 463.05 expected, observed/expected ratio (o/e) 0.93, 90% interval 0.86 to 1.01. Synonymous variants: 195 observed, 178.98 expected, observed/expected ratio (o/e) 1.09, 90% interval 0.97 to 1.23.
Homologues: Orthologues: chimpanzee NCF4 (97% identical), rabbit NCF4 (90% identical), dog NCF4 (90% identical), guinea pig NCF4 (88% identical), mouse Ncf4 (86% identical), pig NCF4 (86% identical), rat Ncf4 (78% identical), macaque NCF4 (76% identical), zebrafish ncf4 (57% identical), tropical clawed frog ncf4 (52% identical), Caenorhabditis elegans sorb-1 (17% identical), Caenorhabditis elegans B0303.7 (16% identical), and 1 more. Paralogues in human: SORBS1 (19% identical), SORBS2 (19% identical), SH3D19 (19% identical), SORBS3 (19% identical), SH3RF3 (18% identical), SH3GL2 (17% identical), SH3GL1 (16% identical), SH3RF1 (16% identical), SH3GL3 (15% identical), SH3GLB2 (13% identical), SH3RF2 (13% identical), SH3GLB1 (12% identical).
Diseases named in the same sentence as NCF4 in open-access papers:
NCF4 is named in the same sentence as 88 diseases in open-access papers, as found by Europe PMC text mining. Sharing a sentence is not in itself a finding about the gene and the disease. The quoted sentences say what the papers report.
chronic granulomatous disease (20 papers, 2016 to 2025). Chronic granulomatous disease (CGD) is a rare primary immunodeficiency, mainly affecting phagocytes, which is characterized by an increased susceptibility to severe and recurrent bacterial and fungal infections, along with the development of granulomas. "Due to its important role in the innate immune response, the gene polymorphism of NCF4 has been reported to be involved in chronic granulomatous disease and increased the risk of colorectal cancer." (PMID 32746852, 2020). "The protein encoded by this gene is part of the NADPH oxidase complex; NCF4 participates in reactive oxygen species-induced phagocytosis in neutrophils, and mutations in this gene have been described as a cause of chronic granulomatous disease due to defects in NADPH oxidase." (PMID 31009519, 2019). "In particular, Nox2 oxidase function deficiency in phagocytes due to genetic variants (CYBB, CYBA, NCF1, NCF2, and NCF4) has been recognized as a direct cause of chronic granulomatous disease (CGD), an inherited immune disorder." (PMID 29867559, 2018). "While heritable genetic defects in neutrophils, such as those causing Chronic Granulomatous Disease (CGD), NCF4 variants, and p22^phox (CYBA) polymorphisms, are known to disrupt ROS production and immune responses, these represent distinct inherited conditions." (PMID 40427426, 2025). "Mutations in the five structural genes (NCF1, NCF2, NCF4, CYBA, CYBB) are associated with chronic granulomatous disease (CGD), a condition characterized by impaired production of reactive oxygen species (ROS)." (PMID 37533075, 2023). "Chronic granulomatous Disease (CGD) is a rare innate immunodeficiency disorder caused by mutations in one of the six genes (CYBA, CYBB, NCF1, NCF2, NCF4, and CYBC1/EROS) encoding the superoxide-producing nicotinamide adenine dinucleotide phosphate (NADPH)—oxidase complex in phagocytes." (PMID 33746979, 2021). "Chronic granulomatous disease is an immunodeficiency disease caused by defects in any of the five structural components of the NOX enzyme, i.e., X-linked recessive mutations in Cybb (gp91phox), or autosomal recessive mutations in Cyba (p22phox), Ncf1 (p47phox), Ncf2 (p67phox), or Ncf4 (p40phox)." (PMID 33842458, 2021).
Crohn disease (10 papers, 2013 to 2024). A gastrointestinal disorder characterized by chronic inflammation involving all layers of the intestinal wall, noncaseating granulomas affecting the intestinal wall and regional lymph nodes, and transmural fibrosis. "In patients with Crohn’s disease who have rs4821544 variants in NCF4, there was a decline in reactive oxygen species following stimulation with the pro-inflammatory cytokine granulocyte-macrophage colony-stimulating factor." (PMID 37628612, 2023). "Mutations in NCF4, the gene encoding p40phox subunit, have been shown to be associated with increased susceptibility for Crohn’s disease." (PMID 33780601, 2021). "In another context, several genetic variants in the NCF4 gene had been associated with autoimmune diseases including RA and Crohn's disease." (PMID 33145364, 2020). "NCF4 is a susceptibility gene that is significantly associated with Crohn’s disease and colorectal cancer, although the details of the mechanism remain unknown." (PMID 38886341, 2024). "NCF4, encoding p40phox, has been associated with rheumatoid arthritis and Crohn’s disease." (PMID 24069023, 2013). "The NCF4, an innate immunity gene, is the part of the NAPDH complex and is associated with an increased susceptibility to Crohn’s disease." (PMID 33101364, 2020). "Variations in NCF2, encoding p67phox, and NCF4, encoding p40phox, have been associated with SLE and with rheumatoid arthritis and Crohn's disease, respectively." (PMID 29430280, 2017). "The associations reported in GWAS between SNP rs4821544 in human NCF4 and Crohn’s disease confirmed the involvement of NADPH genes in the pathogenesis of common inflammatory-related diseases." (PMID 26600390, 2015).
mastitis (8 papers, 2015 to 2025). Inflammation of breast tissue during lactation or postpartum due to an obstructed duct or infection. "It appears that the innate immunity gene neutrophil cytosolic factor 4 (NCF4) is associated with and has an effect on mastitis in cattle." (PMID 40005882, 2025). "Functional SNP formed from NCF4 splice variants was associated with mastitis susceptibility in dairy cows, and NCF4 expression was also affected by alternative splicing." (PMID 34946806, 2021). "This study proposes that NCF4 splice variants generated by functional SNP are important risk factors for mastitis susceptibility in dairy cows." (PMID 26600390, 2015). "Consequently, a study reported that the miRNAs-mRNA interaction significantly regulates the expression of NCF4, which is linked with mastitis susceptibility and host immunity." (PMID 36911690, 2023). "In this study, we hypothesized that the bovine NCF4 gene may play an important role in bovine mastitis susceptibility, which is regulated by alternative splicing." (PMID 26600390, 2015). "Therefore, we attempt to clarify the potential molecular mechanism of NCF4 expression and its relationship to mastitis caused by pathogenic bacterial infection." (PMID 26600390, 2015). "However, knowledge remains limited with regard to alternative splicing events and characterization of the NCF4 splicing mutation, as well as their roles on cattle mastitis susceptibility." (PMID 26600390, 2015). "Cattle mastitis appears to be related to and influenced by the innate immunity gene neutrophil cytosolic factor 4 (NCF4)." (PMID 39195794, 2024). "Another study found an SNP on g.18475 A>G in the 3′ UTR of NCF4, which was linked with higher levels of milk SCC, suggesting its critical role in mastitis susceptibility." (PMID 36911690, 2023). "NCF4 has been shown to be upregulated in mastitic mammary glands, and two SNPs mapping to the NCF4 gene have been associated with elevated somatic cell scores (SCS), a trait that is used as a surrogate phenotype for mastitis in dairy animals." (PMID 30678637, 2019). "Since cows suffering from mastitis produce smaller volumes of milk than healthy cows, this provides a possible mechanism by which NCF4 could influence milk production." (PMID 30678637, 2019). "NCF4 is an essential innate immunity gene with an important role in bovine mastitis." (PMID 26600390, 2015). "The SNP g.18174 A>G of NCF4 may contribute to genome-assisted selection of SNP panels to improve mastitis resistance traits on a breed basis." (PMID 26600390, 2015). "The innate immunity gene neutrophil cytosolic factor 4 (NCF4) appears to be relevant and to be involved in the development of mastitis in cattle." (PMID 37368756, 2023).
colitis (6 papers, 2013 to 2024). Inflammation of the colon. "ROS inhibitors NAC and DPI were also demonstrated to have a positive effect in attenuating DSS-induced colitis and colitis-associated colorectal cancer in both mice and humans, indicating that NCF4 might prevent colorectal cancer progression through functions other than ROS alone." (PMID 38886341, 2024). "In one reported case, autosomal recessive inheritance of two NCF4 (p40phox) null alleles was associated with a unique clinical profile relative to other forms of CGD and manifested as severe colitis resembling IBD6." (PMID 26194095, 2015). "Likewise, Ncf4–/– mice exhibited more body weight loss and reduction of colon length compared with WT mice in the DSS-induced colitis model, whereas ROS inhibitors NAC or DPI and APO significantly inhibited the disease progression." (PMID 38886341, 2024). "However, since Ncf4 interacts directly with Ncf2, knocking out p40phox might induce a broader phenomenon, making it difficult to assess which is the unique contribution of p40phox to colitis severity." (PMID 24873968, 2014).
Arthritis (5 papers, 2020 to 2025). Inflammation of a joint. "Mutations in both Ncf1 and Ncf4 affect development of arthritis in experimental models of RA, but the different regulatory pathways mediated by NOX2-derived reactive oxygen species (ROS) have not yet been clarified." (PMID 38547647, 2024). "For instance, the human gene NCF4 was found to be associated with arthritis as a translation of studies on a rat arthritis model." (PMID 32741357, 2020). "We show that a mutation that hinders NCF4 interactions with endosomal membranes enhances antigen processing and presentation of cysteine-containing peptides, thereby allowing activation of T cells in the draining LNs and increasing arthritis susceptibility." (PMID 38547647, 2024). "When comparing healthy rams to those with arthritis, the expression levels of the following genes were noticeably higher: IL-1α, IL-1β, IL-6, IL-10, TNFα, NCF4, NFKB, TMED, FCAMR, iNOS and COX18." (PMID 40005882, 2025). "The rams with arthritis showed significantly greater levels of gene expression for the genes IL-1α, IL-1β, IL-6, IL-10, TNFα, NCF4, NFKB, TMED, FCAMR, iNOS and COX18 than did the healthy rams." (PMID 40005882, 2025). "Gene expression intensities were much higher in the arthritis-affected rams than in the healthy ones for the genes IL-1α, IL-1β, IL-6, IL-10, TNFα, NCF4, NFKB, TMED, FCAMR, iNOS and COX18." (PMID 40005882, 2025). "Taken together, our findings show that NCF4-mediated intracellular ROS in APCs affect antigen processing of the GPI325-339 peptide and prevent activation of arthritogenic T cells, thus providing protection from arthritis." (PMID 38547647, 2024). "This research described the antioxidant (SOD3, CAT, GPX, ATOX1 and COX18) and immunological (IL-1α, IL-1β, IL-6, IL-10, TNFα, NCF4, NFKB, TMED, FCAMR and iNOS) genes in rams that had arthritis and those that did not." (PMID 40005882, 2025).
colorectal cancer (5 papers, 2020 to 2024). A primary or metastatic malignant neoplasm that affects the colon or rectum. "NCF4 deficiency causes severe colorectal cancer in mice treated with the DNA-damage agent azoxymethane (AOM) and inflammatory agent dextran sodium sulfate (DSS)." (PMID 38886341, 2024). "Reduced NCF4 expression is associated with colorectal cancer development and decreased five-year survival rate in patients with colorectal cancer." (PMID 38886341, 2024). "There is a provided evidence of an association between NCF4 and increased risk of colorectal cancer, whereas the NCF4 rs1883112 were risk factors in diffuse large B-cell lymphoma patients." (PMID 33101364, 2020). "NCF4 deficiency causes severe colorectal cancer in mice, increases transit-amplifying and precancerous cells, reduces the frequency and activation of CD8+ T and NK cells, and impairs the inflammasome-IL-18-IFN-γ axis during the early phase of colorectal tumorigenesis." (PMID 38886341, 2024). "Neutrophil cytosolic factor 4 (NCF4) is associated with the risk of colorectal cancer." (PMID 34497631, 2021). "Here the authors report that NCF4, a subunit of the NOX2 complex, acts a sensor of ROS levels and regulates NLRP3 and AIM2 inflammasome activation, associated with attenuated colorectal cancer progression." (PMID 38886341, 2024). "We performed bioinformatic analysis to assess the gene expression of NCF4, NCF1, and NCF2 in colon tumors and control tissues from 480 colorectal cancer (CRC) patients and 41 paired tumors and associated normal tissues available in the TCGA database." (PMID 38886341, 2024). "Heterozygous Ncf4+/– mice also exhibited aggravated colorectal cancer development." (PMID 38886341, 2024). "Furthermore, in a second independent cancer model, we crossed Ncf4–/– mice with ApcMin/+ mice which spontaneously develop colorectal cancer, and found that colon cancer development and spleen size were significantly increased in the absence of NCF4." (PMID 38886341, 2024). "Furthermore, we demonstrated the essential role of the NCF4-Inflammasome-IFN-γ axis for the activation of NK and CD8+ T cells, which counteract colorectal cancer in the early stages of tumor development." (PMID 38886341, 2024). "Furthermore, a longer five-year survival rate for colorectal cancer patients correlated with a higher expression of NCF4, but not NCF1 or NCF2." (PMID 38886341, 2024).
endometritis (5 papers, 2023 to 2025). An acute or chronic, usually bacterial infectious process affecting the endometrium. "The buffaloes with endometritis had considerably higher expression levels of TLR4, IL-8, IL-17, NFKB, SLCA11A1, NCF4, Keap1, HMOX1, OXSR1, ST1P1, and SERP1." (PMID 39195794, 2024). "Our findings showed that the buffaloes with endometritis had significantly higher TLR4, IL-8, IL-17, NFKB, SLCA11A1, NCF4, Keap1, HMOX1, OXSR1, ST1P1, and SERP1 expression levels." (PMID 39195794, 2024). "TLR4, IL-8, IL-17, NFKB, SLCA11A1, NCF4, Keap1, HMOX1, OXSR1, ST1P1, and SERP1 were manifestly expressed at much higher levels in the buffaloes with endometritis." (PMID 39195794, 2024). "Using PCR-DNA sequencing for the immunological (TLR4, IL10, TLR7, NCF4, TNF-α, and LITAF) genes, there were changes in the nucleotide sequence between endometritis-affected cows and healthy ones." (PMID 37756095, 2023). "Gene expression levels were considerably higher in endometritis-affected cows than in resistant ones for the genes TLR4, TLR7, TNF-α, NCF4, LITAF, OXSR1, TKT, RPIA, and AMPD1." (PMID 37368756, 2023). "The expression levels of the genes TLR4, TLR7, TNF-α, NCF4, LITAF, OXSR1, TKT, RPIA, and AMPD1 were significantly greater in endometritis-affected Holstein dairy cows than in resistant ones." (PMID 37368756, 2023). "When compared to resistant cows, endometritis-affected cows had considerably higher levels of the genes TLR4, TLR7, TNF, NCF4, and LITAF expression." (PMID 37756095, 2023). "The following genes were assessed for their expression levels using real-time PCR in both the normal and endometritis-affected buffaloes: immune (TLR4, IL-8, IL-17, NFKB, SLCA11A1, and NCF4) and antioxidant (SOD, CAT, NDUFS6, Nrf2, Keap1, PRDX2, HMOX1, OXSR1, ST1P1, and SERP1)." (PMID 39195794, 2024). "Nucleotide sequence variations between healthy and endometritis-affected cows were revealed using PCR-DNA sequencing for immune (TLR4, TLR7, TNF-α, IL10, NCF4, and LITAF), antioxidant (ATOX1, GST, and OXSR1), and erythritol-related (TKT, RPIA, and AMPD1) genes were reported by44." (PMID 38459095, 2024). "Nucleotide sequence variations between healthy and endometritis-affected cows were revealed using PCR-DNA sequencing for immune (TLR4, TLR7, TNF-α, IL10, NCF4, and LITAF), antioxidant (ATOX1, GST, and OXSR1), and erythritol-related (TKT, RPIA, and AMPD1) genes." (PMID 37368756, 2023). "Single nucleotide variants (SNPs) in the genes were discovered using PCR-DNA sequencing for immune (TLR4, TLR7, TNF-α, IL10, NCF4, and LITAF), antioxidant (ATOX1, GST, and OXSR1), and erythritol-related (TKT, RPIA, and AMPD1) genes found in resistant and endometritis-infected Holstein dairy cows." (PMID 37368756, 2023). "The immune (TLR4, TLR7, TNF-α, IL10, NCF4, and LITAF), antioxidant (ATOX1, GST, and OXSR1), and erythritol-related (TKT, RPIA, and AMPD1) genes in endometritis-affected and healthy Holstein dairy cows were characterized in this research using a PCR-DNA sequencing technique." (PMID 37368756, 2023). "Molecular genetic analyses of the immunological (TLR4, TLR7, TNF-α, IL10, NCF4, and LITAF), antioxidant (ATOX1, GST, and OXSR1), and erythritol-related (TKT, RPIA, and AMPD1) genes comparing healthy and endometritis cows found differences in nucleotide sequence and transcript levels." (PMID 37368756, 2023).
rheumatoid arthritis (5 papers, 2007 to 2020). A chronic, systemic autoimmune disorder characterized by inflammation in the synovial membranes and articular surfaces. "NCF4 has been associated with ileal Crohn’s disease as well as rheumatoid arthritis in GWAS." (PMID 24069023, 2013).
systemic lupus erythematosus (4 papers, 2015 to 2024). An autoimmune multi-organ disease typically associated with vasculopathy and autoantibody production. "Deletion of the PB1 domain would affect the interaction between NCF4 and NCF2, which is an important risk factor for increased systemic lupus erythematosus, a typical systemic autoimmune disease." (PMID 26600390, 2015).